CD44 (CD44 molecule (IN blood group))
Diseases named in the same sentence as CD44 in open-access papers (continued):
Sharing a sentence is not in itself a finding about the gene and the disease.
tumor (continued). "CD44 is expressed in most human cell types and is implicated in a wide variety of physiological and pathological processes, including lymphocyte homing and activation, wound healing, cell migration, tumor cell growth, metastasis and chemoresistance." (PMID 18096084, 2007). "Strong CD44 expression was associated with low grade (P = 0.04) and small tumour size (P = 0.02)." (PMID 11161384, 2001). "Furthermore, the presence of P. aeruginosa and other tumor-associated microbes can promote the epithelial–mesenchymal transition in tumor tissues and increase the expression of invasion-related molecules such as CD44, CD133, and CD166." (PMID 40911411, 2025). "Layer-by-layer surface modification with hyaluronic acid (HA) and DOX resulted in a multifunctional nanoplatform that could actively target CD44+ overexpressed tumour cells, a characteristic feature of various cancers, associated with tumour progression, metastasis, and resistance to chemotherapy." (PMID 40508567, 2025). "CD44 is a transmembrane adhesion glycoprotein belonging to the class I receptor family, playing a crucial role in a wide range of biological processes, including both physiological mechanisms of homeostasis and pathological changes associated with inflammatory and neoplastic diseases." (PMID 41009438, 2025). "Moreover, tumor expression of CD44, a hallmark of cancer cell “stemness” that promotes tumor survival and proliferation, was upregulated in refractory patients and depleted in the responsive ones, with higher stromal expression of one of its ligands, SPP1, in the responsive group." (PMID 38064127, 2024). "Activation and deactivation of CD44 isoforms regulate the activities of the components of signaling pathways, including enzymes, protein kinase pathways, and transcription factors, which have been found to be associated with tumor initiation progression and aggressive behavior." (PMID 38783892, 2024). "Notably, CD44 exists as several splice variants that may be more or less tumor specific, and future analyses should clarify which variants are dominant in GBM cells." (PMID 38414005, 2024). "Our data showed that deficiency of hsa_circRNA_001676 remarkably repressed the sphere-formation ability of CRC cells in vitro and reduced CD133, CD44, Oct-4 and Nanog levels in tumor tissues in vivo, suggesting that deficiency of hsa_circRNA_001676 could suppress CRC cell stemness." (PMID 37884630, 2023). "Thus, the association between increased expression of CD44 and tumor aggressiveness (including chemoresistance) could simply reflect the role that the hyaluronan/CD44 axis plays in the maintenance and self-renewal capacity of CSC populations." (PMID 37958796, 2023). "Tumour samples from a phase II clinical trial of gastric patients showed a correlation between high CD44 expression and decreased survival, while the addition of vismodegib to chemotherapy to the group presenting high CD44 expression was associated with improved outcome." (PMID 38139085, 2023). "A CD44 dependent assembly and expression of a potent proteolytic complex at the cell surface could explain the pro-invasive effects associated with an increased CD44 expression in tumor cells." (PMID 36876041, 2023). "Furthermore, Her2 and CD44 positive EVs has been associated with tumor recurrence and metastasis." (PMID 35012489, 2022). "Importantly, by systemic expression profiling of isogenic cell clones that exhibited different capabilities of CICs formation, we identified CD44, a well-known membrane protein associated with oncogenic phenotypes, as a negative regulator of CICs formation on tumor cells." (PMID 35436988, 2022). "Moreover, literature meta-analysis data show that CD44 is associated with tumor stage (evaluated with the Classification of Malignant Tumors, TNM) and has been suggested to be an independent factor in reduced overall survival, with its expression correlating with worse prognosis in HCC patients." (PMID 35164326, 2022).
tumor (continued). "Moreover, CD44 variant isoforms are reported to be associated with the tumor metastasis." (PMID 35931675, 2022). "Furthermore, epithelial cells from cancerous tissues showed preferential expression of ITGB1 and CD44, which have been reported to be linked to tumor progression and could act as a receptor for SPP1." (PMID 36612160, 2022). "The standard CD44 isoform (CD44s) is found in most cells, whereas the variant isoforms, with a variable number of exon insertions (designated v1–v10), are primarily expressed on cells during inflammation, lymphocyte maturation and activation, and in several types of tumor cells." (PMID 35267625, 2022). "There is a significant interaction effect for tumour budding between CD44 variant 6 and nuclear β-catenin (p = 0.01 by immunohistochemical expression), suggesting that up-regulation of these proteins could contribute to the formation of tumour buds." (PMID 34884696, 2021). "The HA binds to CD44 at extracellular domain causes conformational changes, which leads to activation of CD44 and recruitment of various other cytoplasmic and membrane-bound cytoplasmic proteins (adaptor molecules) trigger the downstream cell survival, growth and tumour progression pathways." (PMID 34513617, 2021). "However, the role of CD44 variants in tumor progression is discussed controversially." (PMID 34681106, 2021). "However, there are contradictory results regarding whether high or low CD44 expression is associated with worsening clinicopathological features, such as a higher tumour histological grade, advanced tumour stage and poorer survival rates." (PMID 34944493, 2021). "Thus these receptors have been identified as targets in the treatment of specific cancers directly associated with CD44 since the inhibition of the interaction HA-receptors might result in complete abrogation of tumor progression." (PMID 32708202, 2020). "CD44 antigen is a cell-surface glycoprotein that is mainly implicated in cell-cell interactions and cell adhesion and migration in a wide variety of cell activities, including lymphocyte activation, recirculation and homing, hematopoiesis, and tumor metastasis." (PMID 31870454, 2019). "Moreover, both downregulation of CD44 standard splice isoform (CD44s) and dysregulated splicing were described, leading to increased, aberrant CD44 variant splice isoforms (CD44v) that play a role in tumor invasion and as prognostic markers." (PMID 30754655, 2019). "Many functionally distinct isoforms could be encoded by the CD44 gene because of the complex alternative splicing of transcripts, and these isoforms may participate in different oncogenic signalling pathways and play different roles in tumour progression." (PMID 27343550, 2017). "Also, CD44 and CD44v6 upregulation is associated with higher tumour grade and stage." (PMID 29207682, 2017). "Indeed, the expression of CD44 variants has an impact on tumor progression." (PMID 29062810, 2017). "Since cancer is a highly fatal disease, our results investigating the association of functional SNP in CD44 gene may have clinical significance in that they can help to identify interindividual differences in tumor susceptibility, recurrence capacity and chemoresistance among patients." (PMID 27521214, 2016). "Thus, CD44, particularly CD44 variant forms, remains a crucial target for tumor therapy." (PMID 25999946, 2015). "Furthermore, CD44 polymorphisms, alone or in combination, may act as markers for identifying localized gastric adenocarcinoma patients at a high risk of tumor recurrence." (PMID 24699672, 2014). "In addition, 4- to 6-fold elevated CD44 expression is associated with tumor growth and metastasis." (PMID 23213537, 2012). "In bronchial cells, CD44 is associated with stem cells, namely basal cells and type 2 pneumocytes, and may act to anchor these cells to the matrix and be important in migration during repair or neoplasia." (PMID 21819617, 2011).
tumor (continued). "An example is the CD44 gene, encodeing a cell-surface glycoprotein, involved in cell-cell interactions, cell adhesion and migration, which participates in a wide variety of cellular functions including lymphocyte activation, hematopoiesis, and tumor metastasis." (PMID 18974852, 2008). "Particularly, Cd44 has been described as a key feature in E/M states, playing an essential role in tumor progression by promoting both stemness and migration of cancer stem cells, and serving as an important marker for hematopoietic stem cells." (PMID 41193641, 2026). "These nanoparticles loaded with all-trans retinoic acid (ATRA) demonstrated ultrahigh drug encapsulation efficiency (~ 93%) and showed selective uptake in CD44-rich tumor cells both in vitro and in vivo." (PMID 41489768, 2026). "GSEA further highlighted CD44’s involvement in tumor stemness pathways, consistent with enhanced aggressiveness under fatty liver conditions." (PMID 41545340, 2026). "For EV-treated MDA-MB-231 and DLD-1 cells, we found a decrease in the protein expression of CD44 and C24, which are accepted markers for cancer cell populations enriched with tumor-initiating cells, a result that corresponds to the previous reports." (PMID 41684625, 2026). "Osteopontin (OPN) and its receptor CD44 are key mediators of tumor progression, hypoxia-related treatment resistance, and metastatic dissemination." (PMID 42123308, 2026). "CD44, a glycoprotein regulating tumor stemness and adhesion, was functionally tested using recombinant MIF (rMIF)." (PMID 41545340, 2026). "Functional validation via CD44 knockdown and in vivo xenograft assays confirmed that the COL1A1-CD44 axis mediates SOX9 mutation-driven stemness maintenance and tumor progression." (PMID 42218401, 2026). "In this case as well, tumor tissues from mice injected with 2B7 exhibited significant changes in CD44 and EMT marker expression." (PMID 41356204, 2026). "The hyaluronic acid-cinnamaldehyde micelle shell enables CD44-mediated tumor targeting and acidic tumor microenvironment-responsive payload release to mitigate off-target effects." (PMID 42293392, 2026). "These SPP1+ macrophages enhanced tumor cell proliferation, stemness, and migration via CD44-Wnt-BTF3 signaling pathway." (PMID 41993204, 2026). "Macrophage-derived SPP1, in turn, enhanced DHCR7 expression and 27-HC production in tumor cells via CD44, forming a positive feedback loop that reinforced immune suppression." (PMID 42212157, 2026). "Conversely, the high-risk group exhibited significantly higher fractions of Ki-67+/PanCK+ and CD44+/EpCAM+ tiles, reflecting a proliferative tumor and cancer stem cell niche (P < 0.001 for all comparisons)." (PMID 41491099, 2026). "Stemness-associated genes such as GDF15, ALDH1L1, GPC3, AFP, EPCAM, CD44, and CD24 were predominantly expressed in tumor cells, with varying levels across other cell types including CAFs, TECs, and TAMs." (PMID 41493679, 2026). "Aptamer-functionalized liposomes targeting HER2, CD44, and nucleolin have shown enhanced tumor selectivity, improved pharmacokinetics, and strong antitumor activity with reduced systemic toxicity." (PMID 41560835, 2026). "Immunohistochemical analysis of tumor tissues injected with 2B7 revealed decreased expression of the cancer stem cell (CSC) marker CD44, as well as changes in the epithelial-mesenchymal transition (EMT) markers E-cadherin and vimentin." (PMID 41356204, 2026). "PDOs were shown to retain CSC markers (aldehyde dehydrogenase (ALDH), CD133, CD44) and tumor heterogeneity, providing insights into stem cell-induced resistance." (PMID 41050078, 2025). "We found that the proportion of naïve T cells (CD62L+CD44-) remained unchanged on day 15 but decreased by day 24 post-tumor inoculation." (PMID 40777028, 2025).
tumor (continued). "The metastatic clusters 1, 5, 7, and 9 exhibited shorter pseudotimes than did primary tumor cluster 12 and had elevated CD44 expression indicating enhanced stemness (all adjusted P < 0.001)." (PMID 40906645, 2025). "For instance, CD24-/CD44+ breast CSCs are mesenchymal-like, primarily quiescent, and localized at the tumor-invasive front, whereas ALDH+ breast CSCs are epithelial-like and proliferative, and more centrally located." (PMID 39919692, 2025). "To further elucidate the molecular effectors underlying the functional differences between the two tumor cell states, we focused on investigating the role of STAT3, a key regulator enriched in Spc-high/CD44-low cells." (PMID 39930268, 2025). "CD44 glycosylation affects its binding to many important ligands (HA, fibronectin, collagen, etc.)and thereby regulates the tumor microenvironment and cancer cell fate." (PMID 41440277, 2025). "The results of immunohistochemistry (IHC) for CD44 in tumor biopsy samples and ELISA for CD44 protein in serum correlated with those of several studies." (PMID 41440277, 2025). "CD44 is one of the functional receptors of GPNMB and is considered as a surface marker of cancer stem cells, interacting with tumor-associated macrophages." (PMID 41180454, 2025). "CD44 was noted for its potential role in tumor initiation and progression, aligning with cancer stem cell theories." (PMID 40005368, 2025). "Similar results were observed with IT injection of EGFR‐targeted LNPs encapsulating GFP mRNA, showing higher GFP expression in CD44‐tumor cells compared to naked LNPs or isotype‐LNPs." (PMID 39736115, 2025). "The expression of CD44 was correlated with the tumor grade, such as HGSC, endometrioid, mucinous, and Ki67 expression." (PMID 41154374, 2025). "Using CD44-mediated nanocarriers to deliver both agents is expected to enhance tumor suppression while minimizing toxicity." (PMID 40259468, 2025). "For CD44, we observed a general trend of higher expression in tumor tissues across most cancer types studied." (PMID 39977830, 2025). "The depletion of CD44 was associated with reduction in hypoxia, EMT, as well as improved mitochondrial metabolism in primary tumor." (PMID 40438109, 2025). "Flow cytometry analysis studies further reveal that tumor cells with elevated CD44 expression exhibit persistent adhesion on HA-functionalized surfaces." (PMID 40988643, 2025). "Resveratrol, a polyphenol found in grapes and red wine, has been shown to downregulate CD44 expression in BC cells, potentially reducing tumor cell adhesion, migration, and invasion." (PMID 40443562, 2025). "Inhibiting proteases such as ADAM10 or γ-secretase can reduce CD44 shedding, thereby inhibiting its contribution to tumor growth and metastasis." (PMID 41440277, 2025). "Immunohistochemistry analysis revealed that protein was mainly expressed in cytoplasm of tumor cells for CD44, CD90, and CD133, while EpCAM was mostly expressed in cell membrane." (PMID 40791212, 2025). "Further, this study demonstrated that the expression of CYP27B1 in the tumor tissues of BC patients was negatively associated with CD200R, CD204 and CD44." (PMID 41374952, 2025). "Initially, the association of YAP and TAZ with SOX2 was re-validated by isolating the CD44+/CD24− cell population from patient tumor samples." (PMID 39979255, 2025). "Overall, these results indicated high stemness of tumor peripheral is due to a predominant localization of CD44+ CSCs in this area." (PMID 40069574, 2025). "Young CAR-T cells are able to persist long-term in vivo, generating a pool of CD44+CD62L+TCF1+ CAR-T cells in the spleen that can potentially generate tumor-specific TEM cells that can migrate to the tumor microenvironment (TME)." (PMID 40394194, 2025). "In vivo imaging confirmed efficient tumor accumulation of HA-coated NPs with minimal off-target distribution, validating CD44-mediated active targeting as a powerful strategy for CRC therapy." (PMID 41440901, 2025).
tumor (continued). "In tissue samples from renal cancer patients, CD44 expression is significantly positively correlated with tumor microvessel density, size, grade, and stage, and it also shows a significant correlation with VM." (PMID 41019994, 2025). "These processes drive the expression of genes involved in cell survival, proliferation, and migration, establishing a feedback loop that amplifies CD44′s role in tumor progression and metastasis." (PMID 41440277, 2025). "Crucially, this combination regimen effectively disrupts key oncogenic signaling networks within Cluster of Differentiation 44 (CD44)-positive tumor-initiating cells." (PMID 41463034, 2025). "In conclusion, our study identified CD44 as a critical player in the survival and recovery of dormant tumor cells following HER2 inhibition." (PMID 40430044, 2025). "Although Combos 1&2 expressed decreased proliferative tumor cells (Ki67+, Vim+, CD44+) these immunologically cold micro-metastases displayed elevated levels of exhaustion markers PD-L1 and PD-1." (PMID 40568104, 2025). "Many investigators have shown increased efficacy in cell and animal tumor models by conjugating drugs to HA or anti-CD44 antibodies and incorporating drugs or siRNAs into vehicles decorated with HA or antibodies." (PMID 40001633, 2025). "CD44, a hyaluronan receptor, regulates cell adhesion, migration, and EMT and is associated with increased tumor aggressiveness and poor prognosis." (PMID 40868290, 2025). "Our findings of grade versus staining intensity of CD44 expression by tumor cells in OOSCC came out to be statistically significant (p < 0.05)." (PMID 40291275, 2025). "A statistically significant correlation was found between the expression of CD44 with patients’ age, size of tumor, histological grade, and HER2/neu hormonal marker." (PMID 40881916, 2025). "CD44 interacts with the tumor microenvironment, influencing its remodeling, and also supports the formation of pre-metastatic niches through adhesion to the extracellular matrix and localization of proteases, such as MMP-9, on the cell surface." (PMID 41009438, 2025). "In the current version of the WHO classification, co-expression of nuclear OTP and CD44 is a prognostic factor for PC tumour patients." (PMID 38896236, 2025). "EphA2 overexpression in the tumor significantly downregulated surface activation markers CD44, CD69, and CD25 on CD8+ T cells via flow cytometry." (PMID 40867322, 2025). "In ESCC, microRNA-34a suppresses tumor progression by directly targeting CD44, thereby inhibiting invasion and metastasis." (PMID 41208974, 2025). "This interaction promotes the stabilization and expression of SLC7A11, thereby supporting ferroptosis resistance and tumor growth, emphasizing the critical role of the CD44/OTUB1-SLC7A11 pathway." (PMID 40259468, 2025). "Pathway-level breakdown revealed that CaWP cells exhibited enhanced outgoing signaling via COLLAGEN, FN1, LAMININ, and CD44 axes—key mediators of extracellular matrix organization and tumor–stroma interaction." (PMID 41561767, 2025). "CD44, a CSC marker and EMT regulator, generates multiple isoforms including CD44s and CD44v, both linked to increased tumor proliferation and invasiveness." (PMID 40761481, 2025). "Twenty-four (47%) cases with CD44 positivity were in the group of tumor size T2, followed by 14 (27.4%) cases in T1 and 8 (15.6%) cases in T3." (PMID 40881916, 2025). "The overexpression of CD44+ on tumour cells allows HA to enhance the selective delivery of DOX, improving drug uptake in malignant cells while minimising toxicity to healthy tissues." (PMID 40508567, 2025). "CD44 cleavage, also known as shedding, is a key process in cancer progression and contributes to tumor invasion, metastasis, and cellular signaling." (PMID 41440277, 2025). "The expression of CD44 on tumor cells in B-cell acute lymphoblastic leukemia indicates a risk of relapse after the elimination of the primary lesion." (PMID 39851489, 2025).